IQSEC2 (IQ motif and Sec7 domain ArfGEF 2)
Diseases named in the same sentence as IQSEC2 in open-access papers (continued):
Sharing a sentence is not in itself a finding about the gene and the disease.
X-linked intellectual disability (5 papers, 2017 to 2024). An X-linked intellectual deficiency in which not enough information is known, reported or published to indicate whether a gene causes non-syndromic or syndromic presentations. "Moreover, mutations in the GEF BRAG1/IQSec2 have been associated with the nonsyndromic X-linked intellectual disability." (PMID 33922618, 2021).
Encephalopathy (4 papers, 2019 to 2023). Encephalopathy is a term that means brain disease, damage, or malfunction. "Genotype/phenotype correlation study in IQSEC2-related encephalopathy should take into account the sex of patients and variant type." (PMID 30206421, 2019). "This study provides a comprehensive overview of IQSEC2-related encephalopathy in males and females, and suggests that an accurate dosage of IQSEC2 at the synapse is crucial during normal brain development." (PMID 30206421, 2019). "A wide phenotypic spectrum for IQSEC2-related encephalopathy is reported." (PMID 37761403, 2023). "Before genetic diagnosis for IQSEC2, descriptive diagnosis before the genetic diagnosis of IQSEC2-related encephalopathy was reported for n = 7 patients (#2, #5, #6, #10, #12, #13, #17), whereas a psychiatric disorder of unlikely genetic origin was suspected for n = 3 patients (#3, #9, #19)." (PMID 37761403, 2023). "Recently, the provocative hypothesis of IQSEC2-related encephalopathy as a phenotypical extension of the “RTT spectrum continuum” has been raised." (PMID 37761403, 2023). "The relationship between IQSEC2-related encephalopathy and precocious puberty is unclear to date." (PMID 37761403, 2023). "In conclusion, our study provides evidence that IQSEC2 encephalopathy is related to the longest synaptic isoform and that females are on average less affected than males, suggesting that a correct dosage of IQSEC2 protein at the synapse is crucial for normal brain development." (PMID 30206421, 2019). "To date, the prevalence of IQSEC2-related encephalopathy is unknown." (PMID 37761403, 2023).
Rett syndrome (4 papers, 2023 to 2026). A severe neurodevelopmental disorder affecting the central nervous system. "Wide phenotypic diversity has been described for IQSEC2-related ID, as is also the case for Rett syndrome (RTT)." (PMID 37048050, 2023).
Anxiety (3 papers, 2019 to 2021). Intense feelings of nervousness, tension, or panic often arise in response to interpersonal stresses. "We found that the overexpression of IQSEC2 in the mPFC unaltered the anxiety, social interaction, social preference, social novelty preference, and novel object preference, suggesting that overexpression of IQSEC2 does not affect social behaviors." (PMID 34685703, 2021). "The time spent in the center and the vertical activity that indicate anxiety level were unaltered in the IQSEC2 KO mice." (PMID 34685703, 2021).
developmental delay (3 papers, 2017 to 2022). "This conclusion suggests that a genetic diagnosis of IQSEC2 mutations is necessary for children with global developmental delay and seizures." (PMID 36267700, 2022). "Our study found four novel IQSEC2 mutations related to overall developmental delay and seizures." (PMID 36267700, 2022).
Neurodevelopmental delay (2 papers, 2021 to 2025). "This is consistent with the clinical course of male children with the S1474Q*fs133 mutation, who have a more profound growth and neurodevelopmental delay than children with other IQSEC2 mutations." (PMID 40427528, 2025). "Our studies provide mechanistic insights into severe infantile epilepsy and neurodevelopmental delay associated with this mutation and present a human model for studying IQSEC2 mutations in vitro." (PMID 34535765, 2021).
chronic myeloid leukemia (1 paper, 2017). "Pathways of chronic myeloid leukemia, adherens junction, apoptosis, and endocytosis were enriched in up-regulated genes, except IQ motif and Sec7 domain 2 (IQSEC2) genes in pathways in endocytosis." (PMID 28368324, 2017).
growth deficiency (1 paper, 2023). "Interestingly, this patient showed a severe somatic growth deficiency (BW z-score −2.33 vs. −0.07 ± 1.3 no-SMARCC1 co-mutated IQSEC2 patients, height z-score −1.88 vs. 0.05 ± 1.1, BMI z-score −2.33 vs. −0.17 ± 1.42, and head circumference z-score −2.05 vs. −0.86 ± 1.02)." (PMID 37761403, 2023).
muscle disorders (1 paper, 2024).
obstructive sleep apnea syndrome (1 paper, 2023). Cessation of air flow during sleep due to upper airway obstruction. "Interestingly, obstructive sleep apnea syndrome (OSAs) was reported in n = 4 female IQSEC2-mutated patients." (PMID 37761403, 2023).
neurodevelopmental disorder (5 papers, 2021 to 2025). A behavioral and cognitive disorder with onset during the developmental period that involves impaired or aberrant development of intellectual, motor, or social functions. "In this study, we examined the behavior and synapse function in IQSEC2 knockout (KO) mice that we generated using CRIPSR/Cas9-mediated genome editing to solve the relevance between IQSEC2 deficiency and the pathophysiology of neurodevelopmental disorders." (PMID 34685703, 2021). "The IQSEC2 protein plays a key role in glutamatergic synapses and mutations in the IQSEC2 gene are a frequent cause of neurodevelopmental disorders." (PMID 33888678, 2021). "To study the relevance between IQSEC2 deficiency and neurodevelopmental disorders, we studied behaviors in IQSEC2 KO mice." (PMID 34685703, 2021). "While the molecular function of IQSEC2 has gradually been unlabeled by previous studies, the relevance between IQSEC2 deficiency and the pathophysiology of neurodevelopmental disorders has not been addressed." (PMID 34685703, 2021). "The findings of this study may therefore be broadly relevant for a large number of neurodevelopmental disorders of different etiologies and not just for this one mutation in IQSEC2." (PMID 33888678, 2021).
tumor (1 paper, 2023). "The intersection set analysis of the bioinformatics database and transcriptome array data identified six common genes, FSTL1, GDF15, IQSEC2, KDM3A, LTC4S and TCTEX1D4, in which most of them were involved in tumor cell proliferation and growth." (PMID 38201443, 2023). "These genes were FSTL1, GDF15, IQSEC2, KDM3A, LTC4S and TCTEX1D4, in which most of them were involved in tumor cell proliferation and growth." (PMID 38201443, 2023).
IQSEC2 also shares sentences with these, for which no sentence is quoted: Dravet syndrome (2 papers); gastric cancer (2); microcephaly (2); schizophrenia (2); 18q deletion syndrome (1); channelopathies (1); Cockayne syndrome (1); cognitive deficits (1); developmental and epileptic encephalopathy (1); genetic disorder (1); infantile epilepsy (1); infantile spasms (1); infection (1); Lennox-Gastaut syndrome (1); metabolic disorders (1); mucolipidosis II (1); neurologic disorders (1); neuronal migration disorders (1); Onset (1); psychiatric disorder (1); Salla disease (1); Sleep disturbance (1); Strabismus (1); tethered spinal cord syndrome (1); tuberculosis (1).